CYP2R1 (cytochrome P450 family 2 subfamily R member 1)
Diseases named in the same sentence as CYP2R1 in open-access papers (continued):
Sharing a sentence is not in itself a finding about the gene and the disease.
seminoma (1 paper, 2023). A radiosensitive malignant germ cell tumor found in the testis (especially undescended), and extragonadal sites (anterior mediastinum and pineal gland). "Using TCGA mRNA expression of anabolic (CYP2R1, CYP27A1 and CYP27B1) and catabolic (CYP24A1) Vitamin D enzymes, positive (PTHLH, IFNG, and TNF) and negative (FGF23) feedback regulators could also clearly distinguish between pure seminomas and NSGCT." (PMID 37242266, 2023).
thyroid autoimmunity (1 paper, 2015). "Recently, several genetic studies have demonstrated an association between thyroid autoimmunity susceptibility and gene polymorphisms of numerous proteins and enzymes that are associated with vitD functions, including VDR, DBP, CYP27B1, and CYP2R1." (PMID 26681939, 2015).
varicocele (1 paper, 2022). A condition characterized by the dilated tortuous veins of the spermatic cord with a marked left-sided predominance. "Scanty evidence is currently available on the effect of varicocele on testicular CYP2R1 enzyme, which hydroxylases vitamin D into 25(OH)D." (PMID 35160168, 2022).
vitamin D-dependent rickets, type 1 (1 paper, 2024). Hypocalcemic vitamin D-dependent rickets (VDDR-I) is an early-onset hereditary vitamin D metabolism disorder characterized by severe hypocalcemia leading to osteomalacia and rachitic bone deformations, and moderate hypophosphatemia. "Mutations in CYP27B1 lead to 1α-hydroxylase deficiency, known as vitamin D-dependent rickets type 1 or hereditary pseudo-vitamin D-deficient rickets, while mutations in CYP2R1 result in 25-hydroxylase deficiency." (PMID 38892599, 2024).
Vogt-Koyanagi-Harada disease (1 paper, 2022). A bilateral, chronic, diffuse granulomatous panuveitis typically characterized by serous retinal detachment and frequently associated with neurological (meningitis), auditory, and dermatological alterations. "In a cohort of patients with Vogt-Koyanagi-Harada disease, a non-synonymous variant of CYP2R1 was found in 17 of 39 patients, suggesting that the variant in CYP2R1 may play a role in VKH pathogenesis." (PMID 35457041, 2022).
cancer (11 papers, 2017 to 2025). A tumor composed of atypical neoplastic, often pleomorphic cells that invade other tissues. "Some studies have related the mutated genotype CYP2R1 rs10741657-GG to alterations in vitamin D plasma levels and a worse cancer prognosis, due to malfunctioning of the 25-hydroxylase enzyme caused by this SNP." (PMID 37627104, 2023). "Since the present study is the first meta-analysis to estimate the association between DHCR7 and CYP2R1 SNPs and cancer risk, we consider 0.5 as the FPRP threshold." (PMID 34093899, 2021). "We conducted an integrated review for the correlation of DHCR7 and CYP2R1 SNPs with cancer susceptibility." (PMID 34093899, 2021). "In the meanwhile, a meta-analysis was performed using accessible data to clarify the association between DHCR7 and CYP2R1 SNPs and overall cancer risk." (PMID 34093899, 2021). "Increasing correlational studies were concerned with DHCR7 and CYP2R1 polymorphisms and susceptibility to cancer." (PMID 34093899, 2021). "In the present article, a comprehensive review was performed for the correlation of SNPs in DHCR7 and CYP2R1 genes with overall cancer risk." (PMID 34093899, 2021). "First and foremost, association studies of DHCR7 and CYP2R1 polymorphisms with cancer predisposition remain limited." (PMID 34093899, 2021). "Our aim is to explore the association of DHCR7 and CYP2R1 SNPs with cancer risk, supplying clues to researchers for screening novel cancer biomarkers." (PMID 34093899, 2021). "Nine eligible publications were involved to estimate the association intensity of CYP2R1 polymorphisms and overall carcinoma risk." (PMID 34093899, 2021). "Four SNPs in the CYP2R1 gene were found to be associated with baseline serum 25(OH)D in the D &Cancer study." (PMID 28079136, 2017). "The enzymes DHCR7 and CYP2R1 play critical roles in the metabolism of vitamin D.25Vitamin D may have a role in cancer risk due to its relationship with DHCR7 and CYP2R1 gene polymorphisms, which is why scientists are looking into this." (PMID 38967113, 2024). "The aim of the present study was to explore whether the DHCR7 or CYP2R1 SNPs are related to cancer risk." (PMID 34093899, 2021). "Thus, accumulating researchers were concerned with the correlation between CYP2R1 SNPs and cancer susceptibility." (PMID 34093899, 2021). "Thus, accumulating researchers are concerned with the correlation between polymorphisms of DHCR7 and CYP2R1 genes and cancer susceptibility." (PMID 34093899, 2021). "Overall, we comprehensively assessed the correlation of DHCR7 and CYP2R1 SNPs with carcinoma risk." (PMID 34093899, 2021). "We conducted a Mendelian randomization analysis of the relationship between a vitamin D genetic risk score (GRS, range 0–10), comprised of five single nucleotide polymorphisms (SNPs) of vitamin D status in the DHCR7, CYP2R1 and GC genes and cancer risk among women." (PMID 29315215, 2018). "CYP2R1, CYP27A1 and CYP3A4 are 3 major 25-hydroxylases responsible for the initial hydroxylation to convert vitamin D to 25 (OH)D, and their genetic polymorphisms have been found associated with different risks for developing certain types of cancer." (PMID 40630116, 2025). "Furthermore, we evaluated the association of CYP27B1 rs4646536 and CYP2R1 rs12794714 and rs10766196 polymorphisms with CRC risk in a total of 490 subjects, including 245 CRC patients and 245 non‐cancer controls." (PMID 33058307, 2021). "It was also reported that increased regulation of the vitamin D synthesis gene CYP2R1 and CYP27B1 and vitamin D metabolic genes CYP24A1 leading to changes in vitamin D bioavailability and anti-tumor activity, then influence the development of cancer." (PMID 37644572, 2023). "CYP2R1 and CYP27B1 are dysregulated in different types of cancer, but the mechanism behind the dysregulation is not clearly defined." (PMID 33058307, 2021).
tumor (10 papers, 2016 to 2026). "Less is known about the potential role of the CYP2R1 gene, encoding a major enzyme with vitamin D 25-hydroxylase activity, in neoplasm development." (PMID 36362448, 2022). "CLSTN1 was expressed in both tumor and healthy epithelial cells, while CYP2R1 had almost undetectable expression." (PMID 41145488, 2025). "In C57BL/6 mice bearing E0771 tumors which were fed with the vitamin D-deficient diet and injected with calcitriol (100 IU+cal), we observed an increase in the level of CYP27B1 with an increase in CYP2R1 in tumor tissue." (PMID 33172201, 2020). "When the primary tumours of lymph node positive cases (Dukes C, stage 3) were compared to the paired lymph node metastasis, expression of CYP2R1, CYP8B1, CYP39A1, CYP46A1 and CYP51A1 were each significantly reduced in the lymph node metastasis." (PMID 27341022, 2016). "CYP2R1 expression in 4T1 tumor tissue was the lowest in mice fed with the 5000 and 100 IU diets." (PMID 33172201, 2020). "However, the level of CYP24A1 was the highest in 4T1 tumor tissue from the same treatment group (100 IU+cal), and with the low level of CYP2R1 protein in these mice we observed the lowest plasma level of 25(OH)D3." (PMID 33172201, 2020). "Therefore, the decrease in the level of CYP2R1 observed in 4T1 tumor tissue may be responsible for the increased invasive potential of these cells." (PMID 33172201, 2020).
infection (2 papers, 2023 to 2025). The state of being infected such as from the introduction of a foreign agent such as serum, vaccine, antigenic substance or organism. "It is thought that a severe SARS-CoV2 infection can reduce the concentration of vitamin D in the early stages of infection due to the downregulation of CYP2R1, one of the six cytochromes that catalyze both forms of vitamin D (D2 and D3)." (PMID 37109161, 2023).
cardiovascular disease (1 paper, 2025). "In the present study, we analyzed the CYP2R1, CYP27A1, and CYP27B1 genetic polymorphisms and their association with anthropometric parameters, concentrations of 25(OH)D2, 25(OH)D3, 3-epi-25(OH)D2, 3-epi-25(OH)D3, and 1,25(OH)2D3, in Polish patients with cardiovascular disease and healthy subjects." (PMID 40427592, 2025).
metabolic disease (1 paper, 2022). A congenital disorder (due to inherited enzyme abnormality) or acquired (due to failure of a metabolically important organ) disorder resulting from an abnormal metabolic process. "Recent studies have indicated that both fasting and metabolic diseases suppress the cytochrome P450 (CYP) 2R1, the major hepatic vitamin D 25-hydroxylase." (PMID 35524739, 2022).
CYP2R1 also shares sentences with these, for which no sentence is quoted: acute myocardial infarction (3 papers); tuberculosis (3); atopic dermatitis (2); autoimmune disease (2); endometrial carcinoma (2); gestational hypertension (2); hypophosphatemia (2); non-alcoholic steatohepatitis (2); prostate carcinoma (2); Alzheimer disease (1); autism (1); autism spectrum disorder (1); autoimmune conditions (1); Cirrhosis (1); deficient (1); delirium (1); depression (1); fatty liver disease (1); fibrosis (1); follicular thyroid cancer (1); food allergies (1); Hypercholesterolemia (1); hyperphosphatemia (1); Hypocalcemia (1); hypophosphatemic rickets (1); hypovitaminosis (1); immune disorders (1); iron deficiency (1); ischaemic stroke (1); liver (1).
A further 16 diseases each share a sentence with CYP2R1 in 1 paper.